TMEM151B (transmembrane protein 151B)
Synonyms: C6orf137; TMEM193; bA444E17.5
Tractability: Antibody: UniProt predicts a signal peptide or a membrane-spanning region. PROTAC: its protein half-life has been measured.
Gene: Protein-coding gene on chromosome 6 (44,270,450 to 44,307,506, forward strand). Ensembl gene ENSG00000178233.
Subcellular location: Cell membrane; Endoplasmic reticulum membrane; Endosome membrane
Gene Ontology:
Molecular function: protein binding
Cellular component: endoplasmic reticulum membrane; endosome membrane; membrane; plasma membrane
Genetic constraint (gnomAD): Loss-of-function variants: 21 observed, 30.66 expected, observed/expected ratio (o/e) 0.68, 90% interval 0.49 to 0.99. The upper end of that interval is the gene's LOEUF score, 0.99, which puts it in group 4 of 6, group 1 being the genes least tolerant of losing a copy. Missense variants: 632 observed, 656.74 expected, observed/expected ratio (o/e) 0.96, 90% interval 0.9 to 1.03. Synonymous variants: 333 observed, 282.27 expected, observed/expected ratio (o/e) 1.18, 90% interval 1.08 to 1.29.
Homologues: Orthologues: chimpanzee TMEM151B (99% identical), macaque TMEM151B (99% identical), dog TMEM151B (98% identical), pig TMEM151B (96% identical), rat Tmem151b (94% identical), mouse Tmem151b (93% identical), rabbit TMEM151B (90% identical), guinea pig TMEM151B (87% identical), zebrafish tmem151bb (62% identical), zebrafish tmem151ba (62% identical), Caenorhabditis elegans ZK1067.4 (32% identical). Paralogues in human: TMEM151A (46% identical).
Diseases named in the same sentence as TMEM151B in open-access papers:
TMEM151B is named in the same sentence as 4 diseases in open-access papers, as found by Europe PMC text mining. Sharing a sentence is not in itself a finding about the gene and the disease. The quoted sentences say what the papers report.
breast carcinoma (1 paper, 2021). "Breast cancer patients with higher expression level of TTC34, CNTRL, TMEM151B, hsa-miR-5691, and hsa-miR-92a-1-5p showed the higher OS." (PMID 34055638, 2021). "The results suggested that metastasis associated RNAs, including AHRR, TTC34, CNTRL, ANKRD52, BCAR1, TMEM151B, PANX2, hsa-miR-105-5p, hsa-miR-4435, hsa-miR-5691, hsa-miR-92a-1-5p, and LINC01742 could serve as the prognostic biomarkers of breast cancer patients." (PMID 34055638, 2021).
Insulin resistance (1 paper, 2022). Increased resistance towards insulin, that is, diminished effectiveness of insulin in reducing blood glucose levels. "Genes commonly upregulated in the IR-iPSCs when compared to each IS-iPSC group include EGR1 and MFGE8, which were previously associated with insulin resistance, as well as CD74, SEMA6B, SLFN13, TMEM151B, SLC22A17, and AGRN." (PMID 35987697, 2022).
TMEM151B also shares sentences with these, for which no sentence is quoted: Bell's palsy (1 paper); colon cancer (1).